YPEL5 (yippee like 5)
Description:
Component of the CTLH E3 ubiquitin-protein ligase complex that selectively accepts ubiquitin from UBE2H and mediates ubiquitination and subsequent proteasomal degradation of the transcription factor HBP1. Required for normal cell proliferation (By similarity).
Synonyms: CGI-127
Tractability: Antibody: its Gene Ontology location is reachable by antibodies, with high confidence. PROTAC: ubiquitination databases record sites on it; its protein half-life has been measured.
Gene: Protein-coding gene on chromosome 2 (30,146,771 to 30,160,538, forward strand). Ensembl gene ENSG00000119801.
Subcellular location: Nucleus; Cytoplasm, cytoskeleton, microtubule organizing center, centrosome; Cytoplasm, cytoskeleton, spindle pole; Midbody
Subcellular location (Human Protein Atlas): Cytosol; Nucleoplasm
Pathways (Reactome):
Immune System: Neutrophil degranulation
Gene Ontology:
Molecular function: protein binding
Biological process: cell population proliferation; proteasome-mediated ubiquitin-dependent protein catabolic process
Cellular component: ubiquitin ligase complex; centrosome; extracellular region; ficolin-1-rich granule lumen; GID complex; midbody; mitotic spindle pole; nucleus; tertiary granule lumen; spindle pole
Genetic constraint (gnomAD): Loss-of-function variants: 1 observed, 11.02 expected, observed/expected ratio (o/e) 0.0908, 90% interval 0.031 to 0.43. The upper end of that interval is the gene's LOEUF score, 0.43, which puts it in group 1 of 6, group 1 being the genes least tolerant of losing a copy. Missense variants: 68 observed, 167.75 expected, observed/expected ratio (o/e) 0.41, 90% interval 0.33 to 0.5. Synonymous variants: 61 observed, 59.96 expected, observed/expected ratio (o/e) 1.02, 90% interval 0.83 to 1.26.
Homologues: Orthologues: chimpanzee YPEL5 (100% identical), dog YPEL5 (100% identical), macaque YPEL5 (100% identical), mouse Ypel5 (100% identical), pig YPEL5 (100% identical), rabbit YPEL5 (100% identical), rat Ypel5 (100% identical), tropical clawed frog ypel5 (100% identical), guinea pig YPEL5 (99% identical), zebrafish ypel5 (99% identical), Drosophila melanogaster Ype (70% identical), Caenorhabditis elegans B0546.3 (51% identical), and 1 more. Paralogues in human: YPEL1 (37% identical), YPEL2 (36% identical), YPEL3 (36% identical), YPEL4 (34% identical), DMGDH (24% identical), SARDH (22% identical), PDPR (21% identical), AMT (17% identical), FOXRED1 (14% identical), L2HGDH (12% identical).
Diseases named in the same sentence as YPEL5 in open-access papers:
YPEL5 is named in the same sentence as 8 diseases in open-access papers, as found by Europe PMC text mining. Sharing a sentence is not in itself a finding about the gene and the disease. The quoted sentences say what the papers report.
colorectal cancer (5 papers, 2021 to 2022). A primary or metastatic malignant neoplasm that affects the colon or rectum. "YPEL5 was found to be inhibited by METTL3-m6A (N6-methyladenosine)-YTHDF2 axis in colorectal cancer, promoting the growth and metastasis of tumor." (PMID 35265613, 2022). "For instance, METTL3 facilitated the tumorigenesis and metastasis of colorectal cancer by inhibiting YPEL5 expression in a YTHDF2 (an m6A reader)-dependent manner." (PMID 34950654, 2021). "YPEL5 has been found to inhibit the proliferation of cervical and colorectal cancer cells." (PMID 36290392, 2022). "METTL3 could target the m6A site in the coding sequence region of the YPEL5 transcript and epigenetically repress YPEL5 in an m6A-YTHDF2-dependent manner to promote the growth and metastasis of colorectal cancer." (PMID 35711459, 2022).
chronic lymphocytic leukaemia (2 papers, 2021 to 2022). "Human yippee like 5 (YPEL5) and protein phosphatase 1 catalytic subunit beta (PPP1CBI) genes form recurrent and reciprocal chimeras in chronic lymphocytic leukaemia." (PMID 32951567, 2021). "Increased expression of YPEL5, coding for a member of the carboxy-terminal to LisH (CTLH) complex, has been reported in erlotinib-treated EGFR-mutant non-small cell lung cancer, while recurrent YPEL5-PPP1CB fusion has been reported for chronic lymphocytic leukaemia." (PMID 36045381, 2022).
cervical cancer (1 paper, 2021). A primary or metastatic malignant neoplasm involving the cervix. "In cervical cancer cells, YPEL5 has been shown to play a suppressive role in cell proliferation and cell cycle progression." (PMID 33411363, 2021).
non-small cell lung carcinoma (1 paper, 2021). A group of at least three distinct histological types of lung cancer, including non-small cell squamous cell carcinoma, adenocarcinoma, and large cell carcinoma. "Upregulation of YPEL5 is associated with action of erlotinib in non-small cell lung cancer." (PMID 34178034, 2021).
tumor (5 papers, 2004 to 2023). "Accumulating evidence has underscored the m6A writer METTL3, exhibited an oncogenic potentiality in CRC tumorigenesis recently, wherein it accelerated tumor growth and metastasis through suppressing the expression of YPEL5 in an m6A-YTHDF2-dependent manner." (PMID 37626036, 2023). "Collectively, we identified the pivotal role of METTL3‐catalyzed m6A modification in CRC tumorigenesis, wherein it facilitates CRC tumor growth and metastasis through suppressing YPEL5 expression in an m6A‐YTHDF2‐dependent manner, suggesting a promising strategy for the diagnosis and therapy of CRC." (PMID 33411363, 2021).
cancer (2 papers, 2006 to 2024). A tumor composed of atypical neoplastic, often pleomorphic cells that invade other tissues. "We next made use of the anti-cancer agent tiazofurin to probe the functional link between YPEL5 and NMNAT1 stability." (PMID 38759627, 2024). "Upregulation in cancers was seen in TWISTNB 4, YPEL2 3, CBX3 3, SOX9 8 and β-catenin 7, while downregulation was seen in TWISTNB 6, YPEL2 1, YPEL5 3, SEPT4 2, SEPT6 4, CBX3 3, SOX9 2 and β-catenin 2, compared with those in normal mucosa." (PMID 16504081, 2006). "We note that our study complements work by the Luis Parada laboratory describing similar effects of YPEL5 and WDR26 deletion in mouse cells on NMNAT1 amounts, and on modulating the efficacy of a candidate prodrug in the killing of specific types of cancer cells (personal communication)." (PMID 38759627, 2024).
YPEL5 also shares sentences with these, for which no sentence is quoted: colorectal (1 paper); liver diseases (1).